RNU6-641P (RNA, U6 small nuclear 641, pseudogene)
Gene: Small nuclear RNA gene on chromosome X (36,021,939 to 36,022,045, reverse strand). Ensembl gene ENSG00000206733.
Homologues: Orthologues: chimpanzee U6 (99% identical), guinea pig U6 (92% identical), rabbit U6 (92% identical), macaque U6 (91% identical), mouse Gm24317 (90% identical), pig U6 (90% identical), dog U6 (88% identical), rat U6 (84% identical). Paralogues in human: RNU6-698P (93% identical), RNU6-891P (93% identical), RNU6-1158P (91% identical), RNU6-1316P (91% identical), RNU6-140P (91% identical), RNU6-21P (91% identical), RNU6-25P (91% identical), RNU6-33P (91% identical), RNU6-38P (91% identical), RNU6-48P (91% identical), RNU6-664P (91% identical), RNU6-1 (90% identical), and 1289 more.